GSTM1 (glutathione S-transferase mu 1)
Diseases named in the same sentence as GSTM1 in open-access papers (continued):
Sharing a sentence is not in itself a finding about the gene and the disease.
acute leukemia (6 papers, 2012 to 2025). A clonal (malignant) hematopoietic disorder with an acute onset, affecting the bone marrow and the peripheral blood. "The pooled OR of acute leukemia risks associated with GSTM1 null genotype, GSTP1 Val105 allele and GSTT1 null genotype, were 1.22 (95% CI 1.07–1.38), 1.07 (95% CI 1.00–1.13) and 1.19 (95% CI 1.00–1.41), respectively." (PMID 28902850, 2017). "A significantly elevated association between the null genotype of GSTM1 polymorphism and childhood acute leukemia was found in all subjects (OR = 1.30; 95%CI, 1.11-1.51)." (PMID 24194954, 2013). "The present study suggests that the GSTM1 null genotype is associated with a higher risk of childhood acute leukemia." (PMID 24194954, 2013). "This meta-analysis supports that GSTM1 null polymorphism is capable of causing childhood acute leukemia susceptibility." (PMID 24194954, 2013). "Furthermore, in the stratified analyses of GSTM1 null polymorphism, we found a significant influence on childhood acute leukemia risks in Asian and Black ethnic groups, ALL and population-based controls." (PMID 24194954, 2013). "The GSTM1 polymorphism is one of the most studied loci relating to childhood acute leukemia risk." (PMID 24194954, 2013). "Since then, a number of molecular epidemiological studies have been conducted to examine the association between polymorphisms within the GSTM1, GSTT1 gene and childhood acute leukemia in diverse populations." (PMID 24194954, 2013). "The present meta-analysis, including 3252 cases and 5024 controls from 26 case-control studies, exploring the association of GSTM1 and GSTT1 null polymorphisms with childhood acute leukemia risk." (PMID 24194954, 2013). "To the best of our knowledge, we conducted by far the largest and most comprehensive meta-analysis for quantitative analyses between the roles of the GSTM1 and GSTT1 polymorphisms and childhood acute leukemia risk." (PMID 24194954, 2013). "A systematic review with meta-analysis was performed to investigate the association between GST polymorphisms (GSTM1, GSTP1 and GSTT1) and the development of acute leukemia, since the overall results of existing published studies remained inconsistent with each other." (PMID 28902850, 2017). "Several molecular epidemiological studies have been conducted to examine the association between glutathione S-transferase mu-1 (GSTM1) and glutathione S-transferase theta-1 (GSTT1) null polymorphisms and childhood acute leukemia; however, the conclusions remain controversial." (PMID 24194954, 2013). "To estimate the effect of GSTM1 and GSTT1 polymorphisms on the childhood acute leukemia, as well as to quantify the potential between-study heterogeneity, we conducted a meta-analysis on 26 published case-control studies with a total of 3252 cases and 5024 controls." (PMID 24194954, 2013). "Meta-analysis of case-control studies of GSTM1 and GSTT1 status and the risk of acute leukemia." (PMID 24194954, 2013). "We demonstrated that the null polymorphism of GSTM1 was associated with a significant increase in overall childhood acute leukemia risk, whereas the null polymorphism of GSTT1 did not appear to have an overall influence on the susceptibility of childhood acute leukemia." (PMID 24194954, 2013). "Genotype frequencies of CYP1B1, CYP3A5, GSTT1, GSTM1 and SULT1A1 in females and early age acute leukemia, Brazil, 2000–2012." (PMID 25992585, 2015). "Genotype frequencies of CYP1B1, CYP3A5, GSTT1, GSTM1 and SULT1A1 in males and early age acute leukemia, Brazil, 2000–2012." (PMID 25992585, 2015). "However, molecular epidemiologic case-control studies suggest that children harboring null genotype of the glutathione S-transferase mu-1 (GSTM1) and glutathione S-transferase theta-1 (GSTT1) genes might have an increased risk of the development of childhood acute leukemia." (PMID 24194954, 2013).
acute leukemia (continued). "The association of the GSTM1 null polymorphism but not the GSTT1 polymorphism with childhood acute leukemia may be an indication of substrate specificity of GSTM1 in metabolism of agents that are involved in the etiology of childhood acute leukemia." (PMID 24194954, 2013).
alcoholic liver diseases (6 papers, 2012 to 2025). A disorder caused by damage to the liver parenchyma due to alcohol consumption. "Glutathione detoxification enzymes including Gsta1, Gstm3, Gstm1, Gstp1, Gclm, and Gclc play important roles in protecting against alcoholic liver damage and diseases." (PMID 35565941, 2022). "Glutathione detoxification enzyme genes, including Gsta1, Gstm3, Gstm1, Gstp1, Gclm, and Gclc, play important roles in protecting against alcoholic liver damage and diseases." (PMID 36359319, 2022).
autism (6 papers, 2006 to 2022). Persistent deficits in social interaction and communication and interaction as well as a markedly restricted repertoire of activity and interest as well as repetitive patterns of behavior. "With that proviso, we examine the performance of the proposed test in simulations, and in a new dataset involving the GSTM1 deletion allele and the autism phenotype." (PMID 16472391, 2006). "The full data available, namely case-parent trios along with controls, gives evidence of a heightened risk for autism for GSTM1*0 homozygotes." (PMID 16472391, 2006). "Both analyses support (p = 0.046 for the proposed test, p = 0.028 for the case-control analysis) an association of the homozygous GSTM1 deletion genotype with autism." (PMID 16472391, 2006). "The test is illustrated on a novel dataset showing a genotype relative risk near 2 for the homozygous GSTM1 deletion genotype and autism." (PMID 16472391, 2006). "Polymorphisms in glutathione S-transferase mu 1 (GSTM1), glutathione S-transferase pi 1 (GSTP1), and glutathione peroxidase 1 (GPX1), which modulate the response to oxidative stress, have been associated with increased autism risk." (PMID 21156395, 2011). "Absence of the GSTM1 gene in GSTM1*0 homozygotes could lead to failure of individuals with autism to detoxify important compounds, including some that could be agents or products of oxidative stress." (PMID 16472391, 2006).
chronic myeloid leukemia (6 papers, 2014 to 2020). "According to the function of GSST1 and GSTM1 in the detoxification of exogenous compounds, the individuals carrying deletions have an increased risk for several cancers (colorectal and chronic myeloid leukemia) and toxicities related to medications." (PMID 31324178, 2019). "The aim of the present study is to investigate the association of GSTP1, GSTM1 and GSTT1 gene polymorphisms in susceptibility to Chronic Myeloid Leukaemia (CML)." (PMID 32102530, 2020). "A combination of GSTM1 present and GSTT1 null genotypes have a protective role against susceptibility to chronic myeloid leukemia." (PMID 33083304, 2020).
esophageal cancer (6 papers, 2006 to 2020). A primary or metastatic malignant neoplasm involving the esophagus. "Our data show significant association of “null” GST-genotypes (−/−) with susceptibility to esophageal cancer for GSTM1 (OR = 5.30) and GSTT1 (OR = 3.29) genes." (PMID 23675381, 2013). "Thus, according to the dominant model the risk of esophageal cancer development was significantly higher for the following combinations of genotypes: GSTM1 (± and −/−) (OR = 9.75, p < 0.0001); and GSTT1 (± and −/−) (OR = 3.29, p = 0.02)." (PMID 23675381, 2013). "Our study revealed that deletions of GSTT1 and GSTM1 genes or the distinct point mutations of XRCC1 gene are associated with cervical and esophageal cancers." (PMID 23675381, 2013).
myocardial infarction (6 papers, 2006 to 2025). Gross necrosis of the myocardium, as a result of interruption of the blood supply to the area, as in coronary thrombosis. "Zivkovic et al123 have reported that Serbian individuals with the GSTM1 null genotype exhibit a heightened risk of myocardial infarction." (PMID 40290119, 2025). "In a study conducted in Bangladesh, individuals with the GSTM1 null allele were found to have a 2.5-fold increased risk of experiencing myocardial infarction while those with either the GSTM1 or GSTT1 genotypes exhibited a lower risk." (PMID 40290119, 2025). "The question arises about the association between GSTM1-null genotype and death from myocardial infarction being weaker than that observed for stroke." (PMID 24423050, 2014). "Furthermore, patients carrying both null genotypes for GSTM1 and GSTT1 showed a 3.5-fold higher risk of myocardial infarction." (PMID 40290119, 2025). "This study examined the association between the deletion polymorphisms in GSTM1 and GSTT1 as well as SNPs in GSTA1 (rs3957357) and GSTP1 (rs1695) genes with overall and cardiovascular mortality as well as the death from myocardial infarction (MI) and stroke (CVI) in 199 dialysis patients." (PMID 24423050, 2014). "The effect of GSTM1, GSTT1, GSTP1 and GSTA1 gene polymorphisms on predicting overall and specific cardiovascular outcomes (myocardial infarction, MI or stroke) was analyzed using Cox regression model, and differences in survival were determined by Kaplan-Meier." (PMID 24423050, 2014).
neuropathy (6 papers, 2015 to 2024). A disorder affecting the nervous system that manifests with pain, tingling, numbness, and/or muscle weakness. "Similarly, polymorphisms in GSTM1, the gene encoding the enzyme Glutathione S-Transferase Mu 1, have been associated with a lower incidence of cisplatin-induced neuropathy, while polymorphism of the CYP450 3A enzyme system can necessitate vincristine dose adjustments to prevent neurotoxicity." (PMID 28620280, 2017). "Alternatively, the NRF2 transcription factor serves as a pivotal regulator of the endogenous antioxidant defense and the activation of its downstream target genes, such as HO-1, SOD-1, and GSTM1, is crucial for regulating neuropathy induced by chemotherapy." (PMID 39061924, 2024).
open-angle glaucoma (6 papers, 2008 to 2023). Chronic outflow obstruction of the eye's drainage canals that can lead to increased internal eye pressure and optic nerve damage. "Furthermore the GSTM1-null genotype was associated with higher 8-OH-dG levels and statistically significantly more common in patients with primary open-angle glaucoma (POAG) when compared to control subjects." (PMID 24473138, 2014). "GSTM1 has been reported as the potential gene involved in open-angle glaucoma." (PMID 36431159, 2022).
pancreatic cancer (6 papers, 2000 to 2023). "In contrast, hypermethylation of the GSTM1 gene reduces GSTM1 expression, which is associated with increased gemcitabine susceptibility in pancreatic cancer." (PMID 35936694, 2022). "However, the role of the GSTM1 gene product is only associated with a risk of developing pancreatic cancer and the mechanistic role remains unclear, and warrants further investigation with targeted mechanistic studies on GSTM1 protein." (PMID 36812168, 2023). "While SNPs in the phase I and II metabolism genes CYP1A1, GSTM1, GSTT1 and GSTP1 alone did not correlate with pancreatic cancer risk, a significant interaction between smoking and the GSTT1 null genotype was reported in Caucasian pancreatic cancer subjects." (PMID 24651674, 2014). "Collectively, these preliminary data suggest that GSTM1 and TSPAN8 are upregulated in pancreatic tumors in Black patients we tested in comparison to non-tumorous pancreatic tissue in Black patients and either pancreatic tissue in White patients." (PMID 36812168, 2023).
renal cell carcinoma (6 papers, 2013 to 2025). "Vesna M. Coric’s research showed that the carriers with GSTM1 null genotype is more likely to get renal cell carcinoma." (PMID 30976200, 2019). "Characteristics of the included case-control studies in the meta-analysis of the association between GSTM1 and GSTT1 polymorphisms and the risk of renal cell carcinoma*." (PMID 23717494, 2013). "We performed a quantitative meta-analysis to assess the possible associations between the GSTM1, GSTT1 and GSTP1 genotypes and their individual susceptibilities to renal cell carcinoma." (PMID 23717494, 2013). "Association of GSTM1- and GSTT1-null genotypes, GSTP1 A/G gene polymorphism with renal cell carcinoma (RCC) susceptibility was detected, and the relationship between the GSTM1/GSTT1-null genotype and clinical TNM stages of RCC was assessed, using meta-analysis method." (PMID 29884137, 2018). "Emerging evidences suggest that GSTM1 and GSTT1 are involved in the detoxification of carcinogens, and polymorphisms in this gene that result in a loss of enzyme activity may increase the risk of renal cell carcinoma (RCC)." (PMID 26656529, 2015). "The association of the three Glutathione S-transferases (GSTs) polymorphisms (GSTM1, GSTT1 and GSTP1) genotypes with their individual susceptibilities to renal cell carcinoma (RCC) has not been well established." (PMID 23717494, 2013).
squamous cell carcinoma (6 papers, 1996 to 2021). A carcinoma arising from squamous epithelial cells. "We observed significant associations of GSTM1 deletion polymorphism with the increased risk of both squamous cell carcinoma and adenocarcinoma." (PMID 25797617, 2015). "In this study we show an effect of the glutathione-S-transferase M1 (GSTM1) null phenotype on the risk for squamous cell carcinoma (SCC) of the bladder among male smokers in Egypt, with an adjusted odds ratio of 4.8 (95% confidence interval: 1.06-21.77)." (PMID 8795591, 1996). "Individual studies noted increased GSTM1 deletion in squamous cell carcinoma (SCC) than other LC subtypes, in younger and female LC patients, and in smokers." (PMID 30123431, 2018). "Subgroup analysis showed a significant relationship between squamous carcinoma (SC), adenocarcinoma (AC) or small cell lung carcinoma (SCLC) and GSTM1 null genotype, as well as SC or AC and GSTT1 null genotype." (PMID 25036724, 2014). "The results showed that GSTM1 null genotype vs. present genotype for squamous cell carcinoma, hospitalized patients-based control, smokers and nonsmokers had no heterogeneity with a P value ≥0.05." (PMID 25797617, 2015).
Stroke (6 papers, 2014 to 2023). Sudden impairment of blood flow to a part of the brain due to occlusion or rupture of an artery to the brain. "Homozygous carriers of combined GSTM1*0/GSTA1*A genotype exhibited significantly shorter time to MI or stroke in comparison to ESRD patients carriers of either GSTM1-active or GSTA1*B gene variant." (PMID 24423050, 2014). "The borderline effect modification by wild-type GSTA1*A/*A genotype on associations between GSTM1-null and analyzed outcomes was found only for death from stroke." (PMID 24423050, 2014). "The significant effect modification by GSTA1*A/A genotype on associations between GSTM1-null and analyzed outcomes was found only for the death from stroke." (PMID 24423050, 2014). "The independent significant association between GSTM1*0/0 genotype remained only for the death from stroke as shown by Cox regression analysis." (PMID 24423050, 2014). "When ESRD patients were further stratified according to the specific cause of death (MI or stroke), Kaplan Meier analysis demonstrated a significantly shorter time to death from both cardiovascular causes in patients with GSTM1*0/0 genotype in comparison to those with the active enzyme." (PMID 24423050, 2014). "Furthermore, by the cause-specific analysis of the association between GSTM1 and cardiovascular causes of death, such as MI and stroke, we provided a direct proof of the role of GSTM1 protein in prevention of oxidative stress related cardiovascular complications." (PMID 24423050, 2014). "In the current study, we examined the associations of the GSTs SNPs (Mu 1 (GSTM1) and Theta 1 (GSTT1)), TNF-alpha SNP rs1800629 G > A SNP and VWF SNP rs61748511 T > C with stroke in the Tabuk population." (PMID 37240845, 2023). "Homozygous carriers of combined GSTM1*0/GSTA1*A genotype exhibited significantly shorter time to death of stroke or MI in comparison with carriers of either GSTM1-active or at least one GSTA1*B gene variant." (PMID 24423050, 2014). "Specifically, dialysis patients who were homozygous for both GSTM1*0 and GSTA1*A alleles exhibited a HR of 4.38 (95%CI:1.50-12.75, P = 0.007) for stroke in comparison with carriers of at least one GSTM1-active and/or GSTA1*B allele." (PMID 24423050, 2014). "In accordance with our previous findings these data suggest that the patients with GSTM1*0/0 genotype represent potential candidates for antioxidant therapy with the aim of stroke prevention." (PMID 24423050, 2014). "The interpretation of our results on effect modification by GSTA1*A/A genotype in GSTM1*0/0 individuals regarding the death from MI and stroke should be in the light of the fact that ESRD patients exhibit powerful oxidant stress, and therefore a strong Nrf mediated induction of GST expression." (PMID 24423050, 2014). "Moreover, statistically significant interactive effect existed between GSTM1-null and the GSTA1*A/*A genotype for death of stroke." (PMID 24423050, 2014).
viral infections (6 papers, 2005 to 2025). "Scientific evidence has suggested, in most cases, that nullity of the GSTM1 and GSTT1 genes is associated with worse pathological outcomes and viral infections." (PMID 40867808, 2025). "Another lncRNA named lncRNA-GM binds a large fraction of glutathione S-transferase M1 (GSTM1) during viral infection." (PMID 36439216, 2022). "After virus infection, lncRNA-GM levels rapidly decrease, leading to the promotion of GSTM1-mediated S-glutathionylation of the Cys637 residue in TBK1." (PMID 36439216, 2022). "High risk patients for HC can be identified based on the criteria of: older than 10 years of age, carrying normal CYP2C9 and GSTM1 genotypes, and having viral infections." (PMID 28744217, 2017). "Notably, reduced GSTM1 expression in macrophages enhanced interferon production in macrophage upon virus infection, consistent with our findings." (PMID 36685285, 2022). "Recently it has been shown that interaction between viral infection (especially HPV) and xenobiotic enzymes such as GSTM1 could modulate cancer risk, however the evidence comes from in vitro studies alone." (PMID 15790417, 2005). "Observations from this cohort indicate that in pediatric patients receiving BU-CY regimen prior to allogeneic HSCT age, viral infection status, CYP2C9 and GSTM1 genotype status are important predictors of HC occurrence." (PMID 28744217, 2017).
atopic asthma (5 papers, 2007 to 2022). An asthma that is characterized by symptoms that are triggered by an allergic reaction caused by inhaled allergens such as dust mite allergen, pet dander, pollen and mold. "As for the GSTM1, therewas a-1.5 fold increased risk of atopic asthma in individuals withthe GSTM1 null genotype (OR = 1.5; 95% CI,0.6–3.83), but this increase was not significant." (PMID 17497028, 2007).